SPG11 (SPG11 vesicle trafficking associated, spatacsin)
Description:
May play a role in neurite plasticity by maintaining cytoskeleton stability and regulating synaptic vesicle transport.
Synonyms: KIAA1840; FLJ21439; ALS5; CMT2X
Tractability: Antibody: its Gene Ontology location is reachable by antibodies, with high confidence; the Human Protein Atlas places it where antibodies can reach. PROTAC: ubiquitination databases record sites on it; its protein half-life has been measured.
Target class: Structural protein
Gene: Protein-coding gene on chromosome 15 (44,554,818 to 44,663,688, reverse strand). Ensembl gene ENSG00000104133.
Subcellular location: Cytoplasm, cytosol; Nucleus; Cell projection, axon; Cell projection, dendrite
Subcellular location (Human Protein Atlas): Cytosol; Plasma membrane; Nucleoli
Gene Ontology:
Molecular function: identical protein binding; protein binding; protein kinase binding
Biological process: autophagosome organization; axo-dendritic transport; chemical synaptic transmission; lysosome organization; synaptic vesicle transport; axonogenesis; lysosomal membrane organization; membrane bending
Cellular component: cytoplasm; cytoplasmic vesicle; cytosol; late endosome; lysosomal membrane; lysosome; nucleolus; nucleus; plasma membrane; synapse; axon; dendrite; endoplasmic reticulum
Genetic constraint (gnomAD): Loss-of-function variants: 204 observed, 269.02 expected, observed/expected ratio (o/e) 0.76, 90% interval 0.68 to 0.85. The upper end of that interval is the gene's LOEUF score, 0.85, which puts it in group 3 of 6, group 1 being the genes least tolerant of losing a copy. Missense variants: 3,015 observed, 2,911.6 expected, observed/expected ratio (o/e) 1.04, 90% interval 1 to 1.07. Synonymous variants: 1,117 observed, 1,058.3 expected, observed/expected ratio (o/e) 1.06, 90% interval 1 to 1.11.
Gene-disease validity (ClinGen):
ClinGen rates the evidence that SPG11 causes each of these diseases.
hereditary spastic paraplegia 11 (autosomal recessive): Definitive.
Homologues: Orthologues: chimpanzee SPG11 (99% identical), macaque SPG11 (96% identical), pig SPG11 (86% identical), dog SPG11 (85% identical), rabbit SPG11 (82% identical), mouse Spg11 (76% identical), rat Spg11 (76% identical), tropical clawed frog spg11 (41% identical), zebrafish spg11 (30% identical), Drosophila melanogaster CG13531 (17% identical).
Diseases named in the same sentence as SPG11 in open-access papers:
SPG11 is named in the same sentence as 110 diseases in open-access papers, as found by Europe PMC text mining. Sharing a sentence is not in itself a finding about the gene and the disease. The quoted sentences say what the papers report.
hereditary spastic paraplegia (58 papers, 2010 to 2026). Hereditary spastic paraplegias (HSP) comprise a genetically and clinically heterogeneous group of neurodegenerative disorders characterized by progressive spasticity and hyperreflexia of the lower limbs. "Autosomal recessive hereditary spastic paraplegia is a common and clinical type of familial spastic paraplegia linked to the SPG11 locus (locates on 15q21.1)." (PMID 36239107, 2022). "SPG11-linked hereditary spastic paraplegia is characterized by multisystem neurodegeneration leading to a complex clinical and yet incurable phenotype of progressive spasticity and weakness." (PMID 35906604, 2022). "In patients with hereditary spastic paraplegia with SPG11 mutations, a variety of clinical phenotypes develop due to widespread lesions containing p62-immunoreactive neuronal cytoplasmic inclusions." (PMID 34979968, 2022). "Autosomal recessive hereditary spastic paraplegia (ARHSP) is a common and clinical type of familial spastic paraplegia linked to the SPG11 locus on chromosome 15 in most ARHSP families." (PMID 36239107, 2022). "To investigate the specificity of this finding, we included a cohort of hereditary spastic paraplegia (HSP) patients carrying pathogenic variants in SPG11 (SPG11-HSP)." (PMID 35778567, 2022). "The more detailed genetically guided phenotyping finally confirmed a complicated form of hereditary spastic paraplegia (cHSP) compatible with the homozygous pathogenic variant in the SPG11 gene." (PMID 32214227, 2020). "Mutations in the SPG11 gene are responsible for a severe form of hereditary spastic paraplegia characterized by bilateral weakness, spasticity in the lower limbs, as well as ataxia or cognitive impairment." (PMID 31637311, 2019). "It has also been documented that three proteins associated with cases of hereditary spastic paraplegia (SPG11/spatacsin, SPG15/spastizin, and SPG48/AP-5) are recruited as a complex on the surface of lysosomes and autolysosomes (autophagolysosomes)." (PMID 28036022, 2016). "Although confirmation of compound-heterozygosity could not be performed, our findings enriched the phenotypic spectrum of SPG11 mutations related to hereditary spastic paraplegia." (PMID 37035454, 2023). "Loss‐of‐function SPG11 was identified in hereditary spastic paraplegia patients." (PMID 32864857, 2020). "In addition to ALS phenotype, mutations in SPG11 also cause hereditary spastic paraplegia (HSP) with thin corpus callosum." (PMID 26843957, 2016). "Biallelic loss of SPG11 function constitutes the most frequent cause of complicated autosomal recessive hereditary spastic paraplegia (HSP) with thin corpus callosum, resulting in progressive multisystem neurodegeneration." (PMID 38305941, 2024). "Hereditary spastic paraplegia type 11 (SPG11-HSP) is a complex form of HSP mainly due to mutations in the SPG11 gene." (PMID 37273711, 2023). "Homozygous mutations in SPG11 cause hereditary spastic paraplegia (HSP), a genetic disorder characterized by progressive spasticity and paraparesis." (PMID 38100419, 2023). "Autosomal recessive pathogenic variants in SPG11 are the most frequent cause of complex hereditary spastic paraplegia (HSP)." (PMID 36432490, 2022). "Pathogenic variants in SPG11 are the most frequent cause of autosomal recessive complicated hereditary spastic paraplegia (HSP)." (PMID 34326717, 2021). "Among these genes, SPG11 is the most common cause of complicated autosomal recessive hereditary spastic paraplegia with thin corpus callosum (HSP-TCC), which has been reported to be homozygous or compound heterozygous mutations." (PMID 33430805, 2021). "Another study uncovered the therapeutic potential of GSK‐3β pathway inhibition to restore neurodevelopmental defects in hereditary spastic paraplegia (HSP) patients with SPG11 mutations." (PMID 29997171, 2018). "Mutations in SPG11 cause a complicated autosomal recessive form of hereditary spastic paraplegia (HSP)." (PMID 30574063, 2018).
hereditary spastic paraplegia (continued). "SPG11 mutations are associated with a severe and complex form of autosomal recessive hereditary spastic paraplegias (HSP) with thin corpus callosum." (PMID 29949603, 2018). "Deletions and frameshift mutations in SPG11, lead to hereditary spastic paraplegia (HSP) as well as juvenile recessive ALS." (PMID 28512398, 2017). "Mutations in the Spatacsin (SPG11) gene represent the most common form of autosomal recessive hereditary spastic paraplegia with thin corpus callosum (HSP-TCC)." (PMID 26213621, 2015). "SPG15 and SPG11 are two proteins that are mutated in hereditary spastic paraplegia (HSP), and both proteins have features that are consistent with a role in the AP-5 pathway." (PMID 22022230, 2011). "Mutations in SPG11 are linked to both hereditary spastic paraplegia (HSP) and juvenile ALS." (PMID 40395983, 2025). "Genetic variations in DISC1 were found to modulate prefrontal-limbic connectivity in schizophrenia, and hereditary spastic paraplegia was strongly associated with mutations in SPG4 and SPG11, leading to progressive degeneration of corticospinal tracts." (PMID 40360788, 2025). "Our research adds to the genetic variability associated with the SPG11 and AP4B1 variants and emphasizes the genetic heterogeneity of hereditary spastic paraplegia." (PMID 38906889, 2024). "ZFYVE26 and SPG11, the gene products of ZFYVE26 and SPG11 implicated in two forms of hereditary spastic paraplegia, respectively, form a complex targeted to the lysosome and are also probably functionally closely related." (PMID 34130600, 2022). "SPG11 mutation-related autosomal recessive hereditary spastic paraplegia with thin corpus callosum (HSP-TCC) is the most common cause in complicated forms of HSP, usually presenting comprehensive mental retardation on early-onset stage preceding spastic paraplegias in childhood." (PMID 33430805, 2021). "However, it is clearly important in humans, because mutations in its ζ subunit, encoded by the AP5Z1 gene (aka SPG48), cause hereditary spastic paraplegia (HSP), as do mutations in either SPG11 or SPG15 (SPG is an acronym for spastic paraplegia gene)." (PMID 29381698, 2018). "As our understanding of the hereditary spastic paraplegias increases it is clear that the clinical features are very heterogeneous and the spectrum of signs in disease genes such as SPG11 can vary substantially." (PMID 27544499, 2016). "Some of these candidate genes are involved in other diseases, like SPG11 for example, which is also involved in Hereditary Spastic Paraplegia." (PMID 25299611, 2014). "KIAA0415 was found in an RNAi library screen for genes involved in DNA repair, and SPG11 and SPG15 are two proteins that are mutated in hereditary spastic paraplegia (HSP)." (PMID 22022230, 2011). "This case highlights the phenotypic spectrum of SPG11-associated disease and underscores the importance of ophthalmologic evaluation in patients with hereditary spastic paraplegia, even in the absence of overt visual complaints." (PMID 42078221, 2026). "A progressive axonal degeneration was proven to occur in the cortico-cortical projections (lack of transcallosal inhibition) and cortico-spinal tract (reduced MEP amplitude) in hereditary spastic paraplegia with thin corpus callosum (SPG11 gene) in two sisters with cognitive impairment." (PMID 36225892, 2022). "Hereditary spastic paraplegia SPG11 is characterized by neuronal death in various brain regions." (PMID 31637311, 2019). "This provides a mechanistic explanation for why mutations in AP-5/SPG11/SPG15 cause cells to accumulate aberrant endolysosomes, and highlights the role of endosome/lysosome dysfunction in the pathology of hereditary spastic paraplegia and other neurodegenerative disorders." (PMID 29381698, 2018). "This may explain why the family member of P10, who harbored the GBA1 T408M and SPG11 Q1875* variants, showed no signs of PD nor hereditary spastic paraplegia." (PMID 38153678, 2024).
hereditary spastic paraplegia (continued). "We have previously demonstrated that neuroinflammation by the adaptive immune system acts as a robust and targetable disease amplifier in a mouse model of Spastic Paraplegia, type 11 (SPG11), a complicated form of Hereditary Spastic Paraplegia (HSP)." (PMID 38435059, 2024). "We show that the gene KIAA0415 encodes a putative helicase that interacts with SPG11 and SPG15, two proteins mutated in hereditary spastic paraplegia (HSP)." (PMID 20613862, 2010). "Mutations in the spastic paraplegia genes SPG11, encoding spatacsin, and ZFYVE26, encoding Spastizin (SPG15), cause the most prevalent forms of autosomal-recessive hereditary spastic paraplegia with thinning of the corpus callosum (AR-HSP-TCC)." (PMID 33498913, 2021). "Furthermore, hereditary spastic paraplegia (HSP) is another complex disease that exhibits some genetic overlap with ALS through mutations in ALS2 and SPG11." (PMID 29670510, 2018). "Because of overlapping phenotypes in different hereditary spastic paraplegia (HSP) subtypes, diagnosis of SPG11 is often supplemented with evidence from molecular genetics testing." (PMID 27900367, 2016). "The KIAA0415 interaction partners SPG11 and SPG15, also known as spatacsin and spastizin, are encoded by two genes that have been associated with hereditary spastic paraplegia with thin corpus callosum (HSP-TCC)." (PMID 20613862, 2010). "Other forms of early-onset Hereditary Spastic Paraplegia may present with a similar clinical profile, such as SPG35 (FA2H), SPG79B (UCHL1), SPG11, and SPG15 (usually with even more complicated phenotypes)." (PMID 40757543, 2024).
Cognitive impairment (23 papers, 2015 to 2025). Abnormal cognition is characterized by deficits in thinking, reasoning, or remembering. "Biallelic pathogenic variants in SPG11 are responsible for the complicated form of SPG11, where most patients exhibit cognitive impairment and a thin corpus callosum, in addition to progressive spastic paraplegia." (PMID 39273694, 2024). "Mutations in the SPG11 gene are noted in approximately 60% of patients exhibiting cognitive impairment and thin corpus callosum." (PMID 29949603, 2018). "70% of complex HSP patients presenting with progressive spasticity, intellectual impairment and thin corpus callosum are accounted for by mutations in SPG11/spatacsin and ZFYVE26/spastizin, both having roles in autophagosome maturation and endolysosomal function." (PMID 31142229, 2020). "Learning and memory difficulties are a prominent feature of SPG11 patients and previously published work provided evidence that Spg11−/− mice show cognitive deficits." (PMID 38435059, 2024). "Extending these findings of an overall cognitive impairment in SPG11 patients, we here describe a phenotype of impaired verbal fluency and verbal memory in > 80% of SPG11 patients indicating a frontotemporal neuropsychological phenotype." (PMID 35906604, 2022). "Altogether, combination of MMSE and MoCA confirmed mild cognitive impairment (MCI) in these sporadic SPG11-related HSP-TCC cases." (PMID 33430805, 2021). "General cognitive deficits in SPG11-related HSP-TCC preceding to spastic paraplegia is usually first noticed in childhood for learning difficulties and progresses insidiously to severe functional disability, diagnosed as mental retardation." (PMID 33430805, 2021). "Loss of spatacsin, due to mutations in SPG11, is responsible for a complicated form of HSP where spasticity is often associated with cognitive impairment and lower motor neuron degeneration." (PMID 32180696, 2020). "The cognitive deficit, dysarthria, mental retardation, thin corpus callosum and axonal peripheral neuropathy were highly suggestive of SPG11." (PMID 29980238, 2018). "These include cognitive impairment, thinning of the corpus callosum, and parkinsonism, indicating that the AP-5/SPG11/SPG15 complex contributes to the health of many types of neurons, not just primary motor neurons." (PMID 29381698, 2018). "Cognitive impairment and neuropsychological symptoms including anxiety, learning and memory difficulties, and changes in social behavior are usually present in patients with SPG11." (PMID 38435059, 2024). "In addition to spastic paraparesis, SPG11-related HSP (SPG11–HSP) is commonly characterized by cognitive impairment, thin corpus callosum, and amyotrophy." (PMID 38305941, 2024). "SPG11 is the most common subtype of autosomal recessive HSP with cognitive impairment." (PMID 37712079, 2023). "The patient had onset at the age of 22 years, mainly manifested as spasticity and weakness of the lower limbs, accompanied by mild cognitive impairment (Mini-Mental State Examination score: 24), which was basically consistent with the clinical manifestations of SPG11." (PMID 36923789, 2023). "In particular, cognitive impairment has long been recognized as an important symptom in SPG11." (PMID 35906604, 2022). "Additional symptoms such as cognitive impairment, cerebellar ataxia, epilepsy, retinal degeneration, lower motor neuron damage, and thinning of the corpus callosum characterise spastic paraplegia type-11 (SPG11 or also known as KIAA1840) and spastic paraplegia type-15 (SPG15)." (PMID 41138668, 2025). "Loss of function may affect axonal transport and autolysosomes accumulation, contributing to diffuse neurodegeneration and causing clinical heterogeneity (presenting ataxia, parkinsonism or cognitive impairment in addition to core feature of spastic gait) in SPG11-related HSP-TCC." (PMID 33430805, 2021).
Cognitive impairment (continued). "SPG11 is the most common subtype of AR-HSP, and can present with c-HSP accompanied by cognitive deficits, dysarthria, intellectual disability, thin corpus callosum, and axonal peripheral neuropathy." (PMID 36923789, 2023). "In the present case, although no sign of cognitive impairment and peripheral neuropathy was observed, the characteristic clinical feature of early‐onset, severe spasticity, and corpus callosum atrophy are highly suggestive of the diagnosis of SPG11‐associated HSP." (PMID 33638609, 2021). "Early presentation of bulbar involvement is common in SPG11-JALS, while cognitive deficits and mental health issues are uncommon." (PMID 34946884, 2021). "In previous retrospective studies about SPG11-related HSP-TCC, only 19% (4/21) patients has been reported cognitive impairments at onset, and almost 27% (4/15) patients has described as “TCC without cognitive impairment”." (PMID 33430805, 2021). "Most SPG11 and CTX patients presented major cognitive deficits and scores well below what would be expected for all cognitive functions tested (not only memory)." (PMID 31231294, 2019). "All of the seven SPG11 probands had a complicated form of HSP and showed cognitive impairment: dysarthria 5/7; dysphagia 2/7; nystagmus 3/7; ophthalmoparesis (horizontal gaze) 2/7; cervical dystonia 1/7 and mild ataxia 3/7." (PMID 30778698, 2019). "Of note, SPG11 patients were unable to respond to BDI, because of cognitive impairment." (PMID 31231294, 2019). "Interestingly, the clinical features of neuropathic LSDs are similar to those described in SPG48 patients, as well as SPG11 and SPG15, including cognitive impairment, ataxia, peripheral neuropathy, parkinsonism and spasticity." (PMID 26085577, 2015). "The clinical phenotype of SPG11 and SPG15 are nearly indistinguishable, and are characterized by walking difficulties, progressive spasticity, cognitive impairment, thin corpus callosum, and white matter abnormalities." (PMID 33498913, 2021). "Although early and widespread impairment of cognitive functions across all domains is a well-known phenomenon in SPG11-related HSP-TCC, there are still some cases of TCC without cognitive impairment." (PMID 33430805, 2021).